PRMT5 (protein arginine methyltransferase 5)
Diseases named in the same sentence as PRMT5 in open-access papers (continued):
Sharing a sentence is not in itself a finding about the gene and the disease.
cancer (continued). "Recent evidence shows that PRMT5 is upregulated in a number of cancers, and PRMT5 is an important enzyme involved in tumorigenesis and stem cell maintenance linked to tumor progression and poor prognosis." (PMID 33807786, 2021). "Depletion of PRMT5 inhibits cell proliferation, clonogenic capacity of the cells, and improves the prognosis of cancer patients making PRMT5 an important target for cancer therapy." (PMID 33376131, 2021). "Emerging evidence shows that type II protein arginine methyltransferase 5 (PRMT5) serves as an oncoprotein and plays a critical role in many types of human cancer." (PMID 33495409, 2021). "Both PRMT5 and SND1 are broadly expressed and their deregulation is reported to be associated with a range of disease phenotypes, including cancer." (PMID 33768972, 2021). "Multiple lines of evidence have proven that PRMT5 is attributed to carcinogenic function and have recently received a lot of attention as a potential therapeutic target for cancer and exert their diverse biological functions." (PMID 34124017, 2021). "PRMT5 has unique, pleiotropic regulatory roles in the cytoplasm and nucleus of cancer cells depending on the tissue or cell type in which it is expressed." (PMID 33989303, 2021). "PRMT5 also regulates the cancer growth through methylation of SREBP1 and tissue mSREBP1a R321 SDMA was associated with poor prognosis of HCC." (PMID 34513846, 2021). "Elevated MTA concentrations in MTAP−/− cancer cells provide partial inhibition of PRMT5, which would be enhanced in terms of cancer cell lethality when combined with an inhibitor of PRMT5 directly or with an inhibitor of MAT2A, which supplies SAM for PRMT5." (PMID 33893330, 2021). "The arginine methyltransferase PRMT5 is over-expressed in cancer and has a role in the maintenance of stem cells." (PMID 33579912, 2021). "At present, our knowledge about the mechanism of PRMT5 dysregulation in diseases, especially cancer, is still limited." (PMID 34513846, 2021). "This array of modulators to AKT/GSK3β/β-Catenin highlights that the mechanism of action of PRMT5 will have to be validated in each cancer type, whilst the repeated alterations within this axis argue for its significance." (PMID 34680285, 2021). "Upregulation of PRMT5 in cancer downregulates the apoptotic activity of E2F1, contributing to tumorigenesis." (PMID 34006904, 2021). "Therapeutic targeting of PRMT5 in homozygous MTAP-deleted cancer cells has thus been considered a promising strategy to prevent methylosome organization, selectively killing cancer cells." (PMID 34244484, 2021). "Despite a considerable amount of scientific evidence, it is however still scarcely understood how elevated PRMT5 levels promotes tumorigenesis and cancer progression, especially in CRC." (PMID 33664859, 2021). "PRMT5 levels are up-regulated in several cancers and the depletion of PRMT5 reduces the carcinogenic properties of cells which makes the PRMT5 enzyme as an important therapeutic target for cancer therapy." (PMID 33376131, 2021). "Owing to its methyltransferase activity on the histones and oncoproteins, PRMT5’s role in cancers is entrenched in distinct cellular processes like cell signaling, DNA damage response, gene regulation, and splicing, among others." (PMID 34685445, 2021). "So far, it has been reported that PRMT5 acts as an oncoprotein and plays a crucial role in different types of human cancer via regulation of specific downstream targets or signaling cascades." (PMID 33495409, 2021). "Some selective inhibitors of specific protein methyltransferases, including DOT1L, EZH2 and PRMT5, are currently under clinical investigation as cancer therapeutics." (PMID 33778494, 2021). "The role of PRMT5 in various cancers is particularly well-documented, and investigations into the development of better PRMT5 inhibitors to promote tumor regression are ongoing." (PMID 34685445, 2021).
cancer (continued). "It is worthwhile to note that most of these ASEs were also found in other cancer cell lines following PRMT5 inhibition indicating that these are bona fide consequences of PRMT5 inhibition." (PMID 33579912, 2021). "The oncoprotein PRMT5 promotes cancer cell proliferation, tumorigenesis, tumor invasion, and metastasis, which has been well elucidated in many human cancers." (PMID 33495409, 2021). "The anti-cancer effects of MTDIA indicate that increased cellular MTA inhibits PRMT5-mediated methylations resulting in attenuated tumor growth." (PMID 33893330, 2021). "Genetic depletion of PRMT5 has been reported to impair the viability of cancer cells by promoting G1 cell cycle arrest and apoptosis." (PMID 33953349, 2021). "Upregulation of PRMT5 is found in a number of cancers, and PRMT5 is considered an important enzyme involved in tumorigenesis and stem cell maintenance and is linked to tumor progression and poor prognosis." (PMID 33807786, 2021). "PRMT5, the major enzyme catalyzing the formation of SDMA, has been implicated in cancer biology, and controls expression of both tumor-suppressive and tumor-promoting genes." (PMID 35475236, 2021). "In summary, our analysis showed that PRMT5 is upregulated in multiple carcinomas and is a potential cancer biomarker." (PMID 33953349, 2021). "Emerging evidence reveals that PRMT5 is involved in the regulation of tumor cell proliferation and cancer development." (PMID 34026434, 2021). "Our data indicate that PRMT5 promotes tumorigenesis, progression, and metastasis, suggesting that it is a potential therapeutic target for cancer treatment." (PMID 33953349, 2021). "A growing number of studies have established the role of PRMT5 as a tumor promoting factor in several types of cancers." (PMID 34685445, 2021). "Most of these published studies demonstrate that PRMT5 is overexpressed in many different cancer types, and PRMT5 overexpression correlates with aggressive tumors and poor prognosis." (PMID 33768972, 2021). "Our data indicate that PRMT5 promotes tumorigenesis, progression, and metastasis and suggest that PRMT5 is a potential therapeutic target for cancer treatment." (PMID 33953349, 2021). "Taken together, convincing literature documents the pertinent role of aberrant PRMT5 expression in promoting major cancer hallmarks in hematologic cancers." (PMID 34685445, 2021). "Our findings indicate that inhibition of PRMT5 by shRNA or a pharmacological approach attenuated tumor progression; however, they also induced cancer cell interferon-related gene and PD-L1 expression." (PMID 35111150, 2021). "Based on the co-purification of Snail and the NuRD complex in the PRMT5 interactome and the functions of these components in cancer metastasis, co-IP experiments were performed using HeLa cells." (PMID 33953349, 2021). "From a pathological stand point, aberrant expression of human PRMT5 is observed in diverse cancer types." (PMID 33376131, 2021). "In the context of cancer, PRMT5 is generally regarded as a tumor initiator and promoter of tumor growth." (PMID 34200178, 2021). "While exploring this question was not the focus of this work, understanding how inhibitor mechanism of PRMT5 blockade differentially modulate cancer and immune effects is worthy of further investigation." (PMID 34168658, 2021). "Genetic suppression of PRMT5 has been reported to impair cancer cell growth by inducing senescence and apoptosis." (PMID 33579912, 2021). "Elevated concentrations of MTA are known to inhibit PRMT5, which is essential for cancer cell growth both through its role as a histone methyltransferase and as a regulator of intron splicing." (PMID 33893330, 2021). "Based on this rationale, the combination of a PRMT1 inhibitor and PRMT5 inhibitor synergistically inhibits the proliferation of cancer cells with MTAP deletion." (PMID 34006904, 2021).
cancer (continued). "Protein arginine methyltransferase 5 (PRMT5) overexpression is associated with worse survival and inhibition of PRMT5 results in decreased cancer growth across multiple cancers, including PDAC." (PMID 34680285, 2021). "PRMT5 is overexpressed in various cancers and correlated with poor prognosis, low survival, and drug resistance." (PMID 34103528, 2021). "Overexpression of PRMT5 resulted in an increased sphere-forming rate and volume of cancer cell spheres, whereas knockdown of PRMT5 showed opposite result." (PMID 33953349, 2021). "Tissue microarray analysis by IHC staining revealed significant upregulation of PRMT5 expression in carcinomas from multiple tissues." (PMID 33953349, 2021). "Through modulation of these TFs, PRMT5 can enact a wider repertoire of transcriptional changes related to many essential cellular processes that go awry during cancer progression." (PMID 32456215, 2020). "In all, we highlight the importance of PRMT5 regulation and function in cancer, which provide the foundation for therapeutic modalities targeting PRMT5." (PMID 32743345, 2020). "Chemical inhibition of PRMT5 showed splicing inhibition and anticancer effects across a number of cancer types." (PMID 32481522, 2020). "This fact is reflected in recent studies showing that cancer cells can be sensitized upon PRMT5 inhibition via other mechanisms, unrelated to RNA processing." (PMID 32481522, 2020). "Protein Arginine Methyltransferase 5 (PRMT5) is a transcription regulator for multiple cellular processes that is currently being tested as a potential target in several cancer types." (PMID 32731506, 2020). "PRMT5 upregulation results in increased proliferation and anchorage-independent colony growth, whereas cellular proliferation and colony formation in cancer are significantly inhibited by PRMT5 knockdown." (PMID 32392182, 2020). "We further reported that the PRMT5-NF-κB signaling axis is critical to the progression of many cancers, including colon cancer and pancreatic cancer." (PMID 33375283, 2020). "While we found several cancer signaling pathways enriched in PRMT5 inhibited cells, we also observed a depletion of pathways involved in various DNA repair pathways, such as BRCA1, nucleotide excision repair (NER) and ATM signaling." (PMID 32555249, 2020). "PRMT5 (Protein arginine methyltransferase 5) is upregulated under hypoxia and has many roles in cancer." (PMID 32183388, 2020). "Our results provide additional and strong evidence that PRMT5 promotes cancer cell invasion and migration." (PMID 32709847, 2020). "It therefore appears that both aberrant HH signal activation and PRMT5 and MEP50 overexpression are associated with tumorigenesis and cancer development." (PMID 32859041, 2020). "The protein arginine methyltransferase 5 (PRMT5) is an emerging regulator of cancer and stem cells including adipogenic progenitors." (PMID 33304767, 2020). "Despite the well‐understood oncogenic role of PRMT5, its function outside the cancer field is just beginning to be elucidated." (PMID 33304767, 2020). "We found, using tumour cells where the E2F1 gene had been genetically inactivated combined with chemical ablation of PRMT5 enzyme activity, that E2F1 is important for PRMT5 to maintain cancer cell viability." (PMID 32709847, 2020). "In recent years, PRMT5, as an oncoprotein, has gained increasing attention in terms of cancer prevention and therapy." (PMID 32023548, 2020). "Protein arginine methyltransferase 5 (PRMT5) has been implicated in the development and progression of human cancers." (PMID 31851779, 2020). "Only recently, PRMT5 has been shown to regulate Hsp90A, a known cancer-related chaperone providing protection for a number of oncoproteins." (PMID 32872669, 2020). "Protein arginine methyltransferase 5 (PRMT5) has recently been shown to be aberrantly expressed in various cancers, yet its role in OS remains elusive." (PMID 32023548, 2020).
cancer (continued). "Prmt5 has been showed to promote proliferation and survival of cancer cells, stem cells, and lymphocytes." (PMID 32853367, 2020). "PRMT5 has been found to be upregulated in malignant tumors, such as gastric, lung, and prostate cancers." (PMID 32392182, 2020). "Accordingly, of 949 PRMT-related publications, most have focused on cancer, of which 35% studied PRMT5, 28% PRMT1, and 19% CARM1." (PMID 32743345, 2020). "The results from our study shed light on the important role which E2F1 undertakes in mediating the cancer-relevant effects of PRMT5." (PMID 32709847, 2020). "Given that genetic alterations (amplification, mutation, deletion) are rare in PRMT5 genes, epigenetic control of PRMT5 in cancer emerges as a key player in the control of its expression and activity." (PMID 32743345, 2020). "Recently, PRMT5 has been implicated in EMT by activating the Wnt/β-catenin pathway and inducing cancer cell migration." (PMID 32121248, 2020). "Our results suggest that PRMT5 and E2F1 are linked through a shared pathway of control that impacts on the migration and invasion of cancer cells." (PMID 32709847, 2020). "In the present study, we first analysed the expression of PRMT5 in normal mesothelial and MM cell lines and archival tissue specimens and found that PRMT5 was expressed in both normal and cancer cells, although at a higher level in MM cells." (PMID 32301278, 2020). "To explore at the molecular level the proliferative role of PRMT5 in MTAP‐deleted MM cells, we analysed the effect of PRMT5 knock‐down on the expression of genes involved in cancer cell growth." (PMID 32301278, 2020). "All the normal pleura samples expressed PRMT5, mainly in both nuclei and cytoplasms, although at a lower level with respect to cancer cells." (PMID 32301278, 2020). "Given that PRMT5 participates in a wide range of physiological processes, crucial for maintenance of cancer phenotypes, perturbation of PRMT5 is expected to provide novel means to treat cancer." (PMID 32743345, 2020). "PRMT5 is aberrantly expressed in various cancers and that inhibition or knockdown of PRMT5 suppresses cancer cell proliferation, induces cell cycle arrest, and abolishes cancer metastasis both in vitro and in vivo." (PMID 32023548, 2020). "In light of these findings, PRMT5 is currently being tested as a potential therapeutic target in several cancer types." (PMID 32731506, 2020). "The PRMT5 gene is a key regulator of amplification, migration, and metastasis of malignant tumors and participates in regulation of the cell cycle and autophagy." (PMID 32392182, 2020). "We have recently shown that PRMT5 functions as a master epigenetic activator of DDR genes, and that targeting PRMT5 by genetic knockdown or pharmacological inhibition can sensitize multiple cancer cell lines to radiation and chemotherapy." (PMID 32023548, 2020). "This led to the development of PRMT5 inhibitors for cancer therapy and some are under clinical trials." (PMID 32328070, 2020). "Specifically, knockdown or small-molecule-mediated PRMT5 inhibition significantly limits the growth of cancer cells to improve the overall prognosis of cancer patients." (PMID 32985589, 2020). "To date, it is clear that PRMT5 is an oncoprotein and plays a pivotal role in various human cancer progressions through the regulation of different signalling cascades." (PMID 30461193, 2019). "These interrogations must be addressed to better understand PRMT5 substrate specificity and to further decipher the role of PRMT5 in cancers." (PMID 30957988, 2019). "Of special interest, the expression of PRMT5 has been reported to be correlated with poor prognosis in patients with different cancer types." (PMID 30922330, 2019). "PRMT5 over-expression in cancers is thought to epigenetically silence tumor suppressor and cell cycle genes." (PMID 31694585, 2019).
cancer (continued). "Previous data show that PRMT5-mediated histone methylation directly controls the expression of certain cancer-related genes to promote colorectal oncogenesis." (PMID 30858358, 2019). "Controlling PRMT5 activity is a promising strategy for cancer therapy in situations where host immunity against tumors is attenuated in a FOXP3 dependent manner." (PMID 30800128, 2019). "Particularly, the overexpression of PRMT5 has been correlated with poor prognosis in a variety of cancers." (PMID 31694585, 2019). "PRMT5, a member of the PRMT family, is overexpressed in a wide variety of cancers and its activity is associated with cell transformation." (PMID 31139329, 2019). "Given the links between NF-κB/MYC signaling and PRMT5 induction in cancer as well as between NF-κB/MYC and MS, it is important to investigate the impact of these pathways in T cell PRMT5 expression and pathogenic T cell responses." (PMID 30941147, 2019). "PRMT5 is highly expressed in a variety of cancers, and several inhibitors have been developed that target PRMT5 for cancer therapy." (PMID 31681337, 2019). "Protein arginine methyltransferase 5 (PRMT5), an enzyme which catalyzes the methylation of arginines on histone and non‐histone proteins, has recently emerged as a putative target for cancer therapy." (PMID 30957988, 2019). "MTAP deletion increases dependence on protein arginine methyltransferase 5 (PRMT5) and inhibition of PRMT5 selectively kills MTAP-null cancer cells, indicating that inhibition of PRMT5 is a potential therapy for MTAP-deleted tumors." (PMID 31450721, 2019). "All these observations suggest that PRMT5 is essential for cell proliferation via regulation of cell cycle progression and that PRMT5 is an important upstream effector for cancer cell growth." (PMID 30461193, 2019). "In this study, we present the first characterization of the activity of potent and selective SAM uncompetitive/peptide competitive PRMT5 inhibitors across a broad range of human cancer models." (PMID 29946150, 2018). "Proliferation of OPCs in vivo was not affected by loss of Prmt5 and this was in contrast with previous reports on the effect of PRMT5 inhibition in cancer cells." (PMID 30026560, 2018). "PRMT5 has emerged as an important biomarker for several types of cancer, and increasing evidence argues that enhanced expression of PRMT5 induces proliferative signaling, which drives cancer cell growth and survival." (PMID 30613353, 2018). "Increasing evidence suggests that PRMT5, a protein arginine methyltransferase, has roles in cell growth regulation and cancer development." (PMID 29441724, 2018). "Most cancer cell lines treated with PRMT5 inhibitors exhibit the attenuation of cell growth and survival." (PMID 29946150, 2018). "Together, these results showed that inhibition of PRMT5 reduced cancer cell proliferation and tumor growth." (PMID 29441724, 2018). "It has been proposed that inhibiting the enzymatic function of PRMT5 represents a therapeutic option to treat MTAP mutant cancers." (PMID 29983885, 2018). "PRMT5 dysfunction and/or dysregulation is of particular interest in cancer biology and PRMT5 inhibitors have been researched as potential chemotherapeutics." (PMID 29518110, 2018). "Both transcription factors have been shown to interact with PRMT5 in HEK293 and HepG2 cell lines, highlighting the relevance of this association in increased lipogenesis of cancer cells." (PMID 30613353, 2018). "PRMT5 knock down or inhibition in different cancer cell lines results in increased KLF4 ubiquitylation and turnover, highlighting the crucial role played by PRMT5 in KLF4 protein stability." (PMID 30613353, 2018). "PRMT5 inhibition induced net cell death (net cell growth/death < 0%) in a subset of cancer cell lines at concentrations above 100 nM." (PMID 29946150, 2018). "Overall, the data presented in this paper strongly suggest that PRMT5 inhibitors have therapeutic potential in numerous human cancers." (PMID 29946150, 2018).